TMEM45A (transmembrane protein 45A)
Diseases named in the same sentence as TMEM45A in open-access papers (continued):
Sharing a sentence is not in itself a finding about the gene and the disease.
cancer (18 papers, 2012 to 2025). A tumor composed of atypical neoplastic, often pleomorphic cells that invade other tissues. "In this respect, TMEM45A has been associated with various cancer features, such as cell proliferation, invasion, migration, and Epithelial-Mesenchymal Transition (EMT), and silencing TMEM45A can reverse cisplatin resistance." (PMID 37064154, 2023). "Furthermore, we underlined the complex differential responses upon TMEM45A inactivation according to the cancer cell type." (PMID 31801939, 2019). "The clinical significance of our findings is that high TMEM45A expression could be used as a molecular prognostic marker to identify patients who have an increased risk of cancer relapse after chemotherapy." (PMID 22954140, 2012). "Through gene set enrichment analysis (GSEA), we discovered that TMEM45A promotes cancer cells resistance to CDK4/6i and glycolysis by activating the AKT/mTOR signaling pathway." (PMID 39910045, 2025). "Genes potentially implicated in carcinogenesis were also discovered on this cholangiocyte trajectory: GSTA3, inhibitor of DNA binding 2, and above all, TMEM45A, a transmembrane molecule from the Golgi apparatus considered as oncogenic in several cancers." (PMID 39130146, 2023). "On the NR0B2 cell trajectory of Abcb4−/− cholangiocytes, some molecules implicated in carcinogenesis were evidenced: GSTA3, ID2, and TMEM45A, which is a transmembrane molecule considered to be oncogenic in several cancers." (PMID 39130146, 2023). "In invasive ductal breast carcinoma, the cancer cell expression of the protease inhibitor, CSTA and genes involved in adhesion, FAT1, DST, and TMEM45A, were shown to be involved in cancer invasiveness." (PMID 36114508, 2022). "TMEMs are present in many cell types and participate in a variety of physiological functions such as immune responses (TMEM173), smooth muscle contractions (TMEM16), and cancer (TMEM45A)." (PMID 33600488, 2021). "This study demonstrated, for the first time, an anti or a pro-apoptotic role of this protein depending on the cancer type and highlighted the role of TMEM45A in modulating patient responses to treatment." (PMID 31801939, 2019). "As a result, the following proteins were associated with advanced cancer: TRA-1-60 (9%), TMEM45A (37.5%), pan-keratin (50%), CD326 (100%), MCT4 (50%), GAL-3 (30%), CD66 (100%), GLUT1 (100%)." (PMID 31527554, 2019). "TMEM45A is a transmembrane protein involved in tumor progression and cancer resistance to chemotherapeutic agents in hypoxic condition." (PMID 31801939, 2019). "To identify by which mechanism TMEM45A plays a pro or an anti-apoptotic role according to the cancer cell type, we investigated the impact of cisplatin on DNA damage response." (PMID 31801939, 2019). "Since the expression of this protein has been associated with tumor aggressiveness, we studied the possible role of TMEM45A in cancer resistance to chemotherapies and the mechanism by which it acts." (PMID 31801939, 2019). "This study highlines for the first time the dual role of TMEM45A in drug sensitivity depending of the cancer type." (PMID 31801939, 2019). "In order to investigate the role of TMEM45A in cancer cell chemoresistance, cisplatin sensitivity was determined for different cancer cell lines: SQD9 cells for HNSCC and RCC4 + pVHL for ccRCC." (PMID 31801939, 2019). "For example, in renal cancers, many TMEMs with predicted ER localization have been shown to be potential classifiers of cancer grade (e.g., TMEM45A, TMEM116, TMEM207, TMEM213...)." (PMID 30574087, 2018). "(ii) TMEM45A is expressed in epithelial-derived cancer cells and highly expressed in differentiated keratinocytes, suggesting that it is involved in the normal function of growth arrested epithelial cells." (PMID 22954140, 2012). "In this study, we showed that TMEM45A renders cancer cells resistant to different agents used in chemotherapy." (PMID 22954140, 2012). "TMEM45A is a protein with significant potential in the field of cancer research." (PMID 39910045, 2025).
cancer (continued). "Moreover, attenuation of TMEM45A expression reduces cancer aggressiveness by decreasing the expression of EMT and glycolysis-related proteins." (PMID 39910045, 2025). "For instance, the pattern of PRSS3 downregulation associated with the clinical relevance of HCC patients was similar to that of TMEM45A and VNN1, which are positively co-expressed genes of PRSS3 in HCC patients showing oncogenic effects on cancer-associated events." (PMID 35480112, 2022). "Our data support an implication of TMEM45A in the sensitivity of cancer cells to cisplatin." (PMID 31801939, 2019). "However, little is known about this protein, in particular the mechanisms by which TMEM45A modulates cancer cell chemosensitivity." (PMID 31801939, 2019). "Altogether, these data emphasize the involvement of TMEM45A in tumor aggressiveness and suggest that TMEM45A might be a putative target to develop new chemosensitizing agents at least in some cancer types." (PMID 31801939, 2019). "High levels of TMEM45A expression in tumors may be indicative of potential resistance to cancer therapy, making TMEM45A an interesting biomarker for resistance." (PMID 22954140, 2012). "TMEM45A has been described to be a HIF-1 target gene in different types of cancer cells." (PMID 22954140, 2012). "However, it is not yet clear whether the expression of TMEM45A is related to the response to CDK4/6i treatment in HR + BRCA and whether TMEM45A regulates cancer metabolism." (PMID 39910045, 2025). "However, it has been reported that the inhibition of TMEM45A may increase the chemosensitivity of cancer cells." (PMID 35008313, 2021). "This indicates that TMEM45A may influence cancer cell survival or growth." (PMID 22954140, 2012). "Amongst the genes directly regulated by STAiR18 and STAT3 we identified several targets involved in cell cycle progression and cancer cell survival, like the protein tyrosine phosphatase type 4 member 1 (PTP4A1) and the transmembrane protein 45A (TMEM45A)." (PMID 32041604, 2020). "The following proteins determine trajectories within the pentagram to localize to advanced cancer: TRA-1-60 (9%), TMEM45A (37.5%), pan-keratin (50%), CD326 (100%), MCT4 (50%), GAL-3 (30%), CD66 (100%), GLUT1 (100%)." (PMID 31527554, 2019). "Several other candidate genes were found to be undetectable in whole blood, while most of the genes that were detectable (EGLN3, CAV2, ESM1, TMEM45A, NOL3, FABP7) did not exhibit significant dysregulation in expression between cancer and healthy PAXgene samples." (PMID 32013938, 2020).
tumor (12 papers, 2011 to 2025). "While only TMEM45A was associated with tumor burden status, all of the five signature genes were strongly related to CSG subtypes, suggesting their close relationships with the CSG patterns of HCC." (PMID 36589233, 2022). "In a cell line-derived xenograft (CDX) mouse model, TMEM45A knockdown significantly restores sensitivity to palbociclib and suppresses tumor growth." (PMID 39910045, 2025). "TMEM45A knockdown combination with palbociclib treatment significantly inhibited tumor growth in vivo, suggesting a synergistic effect in the inhibition of tumor progression." (PMID 39910045, 2025). "IHC staining showed that Exo-siTMEM45A knocked down the level of TMEM45A in PDX tumor tissue, indicating that engineered exosomes had a good knockdown efficiency in vivo." (PMID 39910045, 2025). "This approach specifically reduces the expression of TMEM45A within tumor cells, minimizing the toxicity and immune response associated with external delivery vectors." (PMID 39910045, 2025). "Differential expression analysis of TCGA-LIHC tumor tissues and adjacent normal tissues revealed that the expression differences of TMEM45A, S100A10, SERPINA12, BHMT, CFHR3, RPL8, and STMN1 all exceed a 2-fold change." (PMID 39176099, 2024). "TMEM45A transcript was upregulated in tumor tissues compared to healthy tissues in 86% (19/22) and 76% (19/25) of HNSCC and ccRCC samples respectively." (PMID 31801939, 2019). "TMEMs, such as TMEM45A and TMEM205, have also been implicated in tumor progression and invasion but also in chemoresistance." (PMID 30574087, 2018). "Furthermore, we suggest that the dynamic change of ANO1, TMEM38B, TMEM158, and TMEM45A may indicate stellate cell activation and trigger tumor stromal remodeling." (PMID 37265785, 2023). "In summary, we report that TMEM45A promotes glycolysis and palbociclib resistance via the AKT/mTOR signaling pathway in BRCA, leading to enhanced tumor progression." (PMID 39910045, 2025). "Subsequently, TMEM genes expression of stromal cells in normal and tumor tissues was compared, and TMEM158, TMEM38B, VMP1 and TMEM45A were recognized as DEGs." (PMID 37265785, 2023). "Members of this family can act as both oncogenes, such as TMEM45A and TMEM205, or tumor suppressors, such as TMEM25 and TMEM7." (PMID 36077735, 2022). "Although we propose that targeted delivery of siRNA via exosomes derived from primary tumor cells of BRCA patients can effectively suppress the expression of TMEM45A in tumor cells, this method has not yet been translated and validated in clinical settings and thus has certain limitations." (PMID 39910045, 2025). "Furthermore, we verified our findings through immunohistochemical sections of tumor tissue, which indicated that TMEM45A knockdown could suppress the levels of p-AKT and p-mTOR, and the use of SC79 could attenuate the inhibitory effect of TMEM45A knockdown on the pathway." (PMID 39910045, 2025).
TMEM45A also shares sentences with these, for which no sentence is quoted: glioma (3 papers); invasive breast carcinoma (2); adenocarcinoma (1); bladder cancer (1); cholangiocarcinoma (1); clear cell renal cell carcinoma (1); colon cancer (1); ductal carcinoma in situ (1); gastric cancer (1); head and neck cancer (1); head and neck squamous cell carcinoma (1); infection (1); lung (1); pneumothorax (1); preeclampsia (1); psoriasis (1); systemic lupus erythematosus (1).